TYMS (thymidylate synthetase)
Diseases named in the same sentence as TYMS in open-access papers (continued):
Sharing a sentence is not in itself a finding about the gene and the disease.
cervical carcinoma (11 papers, 2012 to 2024). A carcinoma arising from either the exocervical squamous epithelium or the endocervical glandular epithelium. "Some researchers discovered that TYMS expression levels were elevated in cervical cancer and were positively connected with cervical cancer prognosis." (PMID 35994213, 2022). "Studies have shown that RRM2, TK1, and TYMS in cervical cancer tissues are significantly different from healthy tissues and are significantly correlated with overall survival in cervical cancer." (PMID 35082972, 2022). "This study did not further evaluate the potential signaling pathway of miR-197-3p/TYMS in cervical cancer." (PMID 35003215, 2021). "In conclusion, these results reveal that TYMS plays a very important role in the prognosis and progression of cervical cancer, and has the potential to be thought of as cervical cancer biomarkers." (PMID 35003215, 2021). "In conclusion, our data show that TYMS is an independent prognostic gene of cervical cancer, that affects the proliferation, migration, invasion and apoptosis of cervical cancer cells." (PMID 35003215, 2021). "In summary, miR-197-3p, as an upstream regulator of TYMS, affects the progression of cervical cancer through the posttranscriptional effects of TYMS, which is crucial for the tumorigenicity of cervical cancer." (PMID 35003215, 2021). "We also found that the expression level of TYMS was correlated with the tissue grade, tumor grade and age of cervical cancer patients, and TYMS with low expression was more likely to have advanced tumor state, grade and staging." (PMID 35003215, 2021). "Enolase 2 (ENO2) and thymidylate synthetase (TYMS) are found to be upregulated in cervical cancer transcription datasets." (PMID 34790674, 2021). "At the same time, miR-197-3p/TYMS axis can regulate the deterioration of cervical cancer cells, which lays a foundation for the molecular diagnosis and treatment of cervical cancer." (PMID 35003215, 2021). "The results showed that TYMS was significantly down-regulated in cervical cancer, which was consistent with GEO database analysis results." (PMID 35003215, 2021). "To further confirm the regulatory relationship between miR-197-3p and TYMS, we detected the mRNA level of miR-197-3p in cervical cancer tissues." (PMID 35003215, 2021). "We hope to provide more extensive data support for the clinical application of TYMS and the miR-197-3p/TYMS axis in cervical cancer." (PMID 35003215, 2021). "Subsequently, the effects of TYMS and miR-197-3p/TYMS on the progression of cervical cancer were analyzed by gain-of-function analysis." (PMID 35003215, 2021). "MiR-197-3p/TYMS is an effective pair of regulators of cervical cancer, and can provide a good data basis for the treatment of cervical cancer." (PMID 35003215, 2021). "To determine the potential mechanism of TYMS in cervical cancer, we analyzed the potential miRNAs targeted by TYMS using miRWalk and starbase online tools." (PMID 35003215, 2021). "This evidence suggests that miR-197-3p/TYMS plays an important role in the progression of cervical cancer." (PMID 35003215, 2021). "The outcomes of this assessment substantiated our preliminary observations, revealing the upregulation of RRM2 and VEGFA, alongside the downregulation of RFC4, EXO1, PCNA, TOP2A, and TYMS in cervical cancer tissues relative to normal cervical epithelial tissues." (PMID 38926832, 2024). "Through dual-luciferase reporter gene and functional experiments, it was clarified that TYMS may be the target gene of miR-197-3p in cervical cancer." (PMID 35003215, 2021). "Therefore, future research will focus on the potential signaling pathway mechanism and the in vivo regulation of miR-197-3p/TYMS in cervical cancer." (PMID 35003215, 2021). "Similarly, our results suggest that TYMS is a protective factor against cervical cancer and is down-regulated in cervical cancer tissues." (PMID 35003215, 2021).
cervical carcinoma (continued). "However, miR-197-3p directly targeted by TYMS is present a high level in cervical cancer tissues, and up-regulation of TYMS can inhibit the proliferation, invasion and migration of HeLa cells, and promote the apoptosis of HeLa cells." (PMID 35003215, 2021). "GSEA further found that TYMS may be involved in cell cycle, apoptosis, amino acid metabolism and other biological processes in cervical cancer." (PMID 35003215, 2021). "In a similar way, incubation of a nuclear extract from cervical carcinoma cells (HeLa) with the probe produced the same shifted bands (lane 3-4) that could correspond to the binding of the TYMS protein present in the nuclear extract." (PMID 32708710, 2020). "This suggests that TYMS may play a very important role in the progression of cervical cancer." (PMID 35003215, 2021). "Subsequently, we downloaded the expression data of TYMS and the clinical characteristics of cervical cancer patients from TCGA-CESC, and evaluated the relationship between the expression level of TYMS and various clinicopathological parameters." (PMID 35003215, 2021). "Others have shown that CHD8 knockdown in cervical carcinoma cells leads to G1 arrest facilitated by downregulation of CCNE2 and TYMS, genes required for transition into S phase." (PMID 26588464, 2015). "However, the study of TYMS in cervical cancer has not been reported, and its regulatory mechanism on the progression of cervical cancer is still unknown." (PMID 35003215, 2021).
colorectal tumor (10 papers, 1997 to 2025). "A six bp deletion at bp 1494 leads to lower levels of TYMS expression in colorectal tumors, an increased 5-FU sensitivity, and a risk of toxicity whereas a 6bp insertion lead to higher levels of TYMS and poorer prognosis." (PMID 27774364, 2016). "Through immunohistochemistry, it has been found that the immunohistochemical score of TYMS in colorectal tumor tissue was notably higher than that in adjacent tissue." (PMID 39744483, 2025). "TYMS expression was increased in colorectal tumor tissues compared with adjacent tissues (P = 3.00 × 10-4)." (PMID 33046972, 2020). "Differential expression of TYMS was further analyzed in colorectal tumor tissues based on age, sex, CRC family history, BMI and tumor stage." (PMID 33046972, 2020). "In conclusion, MSI colorectal tumors exhibited TYMS and PARP2 upregulation and DFFA downregulation." (PMID 41440189, 2025). "Moreover, we assessed TYMS expression between colorectal tumor tissues and adjacent tissues based on tumor site." (PMID 33046972, 2020). "Additionally, a systematic review and meta-analysis performed in 2004 concluded that colorectal tumors expressing higher TYMS protein levels appear to predict unfavorable prognosis when compared to tumors expressing low levels of TYMS." (PMID 29394274, 2018). "Suppression of TYMS enhanced the efficacy of FdUrd in human colorectal tumor cells." (PMID 27685866, 2016). "Notably, NAA40-mediated activation of the 1C-metabolic gene TYMS confers 5-FU resistance to CRC cells and in human colorectal tumours NAA40 expression positively correlates with TYMS levels and worse response of patients to 5-FU-based chemotherapy." (PMID 34785778, 2022).
COVID-19 (9 papers, 2021 to 2025). A disease caused by infection with severe acute respiratory syndrome coronavirus 2. "In the COVID-19 dataset, TYMS(AUC:0.952), RRM2(AUC:0.954), CDCA2(AUC:0.946) and TOP2A(AUC:0.958) exhibited good diagnostic efficiency for differentiating the patients with SARS-CoV-2 from healthy controls." (PMID 35958619, 2022). "To investigate the cellular origin of TYMS, we acquired snRNA-Seq data, including data from autopsy lung tissues of approximately 116,000 nuclei taken from the lungs of nineteen individuals who died from COVID-19 and seven control individuals from GSE171524." (PMID 38558817, 2024). "Among the ten candidate hub genes, we found that 8 hub genes were differentially upregulated in HBV and COVID-19, so we further narrowed the scope of the study to 8 hub genes, including CDK1, E2F7, E2F8, TYMS, KIF20A, CENPE, TPX2, HMMR." (PMID 40408617, 2025). "TYMS is involved in the CD80/86 proinflammatory axis, and is upregulated in severe COVID-19 patients." (PMID 35746678, 2022). "The advantages of methotrexate in treating COVID-19 are summarized as follows: (a) methotrexate achieves true multi-targeting in COVID-19, by inhibiting multiple targets from diverse protein families like proteases (furin), reductases (DHFR), synthases (TYMS) and transformylase (ATIC)." (PMID 36618412, 2022). "For the remaining five hub genes (TYMS, CDCA2, TOP2A, RRM2 and IFI44), there are no studies reporting their role in COVID-19 or pSS, which emphasizes its importance in future research." (PMID 35958619, 2022).
glioblastoma (9 papers, 2011 to 2022). The most malignant astrocytic tumor (WHO grade IV). "Furthermore, raltitrexed, a specific inhibitor of TYMS used in the therapy of tumour types other than glioblastoma, also effectively blocked cell proliferation in glioblastoma cell lines, thus highlighting this outlier gene candidate as a potential therapeutic target." (PMID 21365010, 2011). "In addition, the GTI identified 29 novel outlier genes in glioblastomas, including TYMS and CDKN2A." (PMID 21365010, 2011). "GTI may therefore identify a putative subset of cancers that may particularly profit from therapy targeting the TYMS gene, which may not be the case for all of the glioblastoma patients." (PMID 21365010, 2011). "Whereas 5FU and gemicitabine also inhibit RRM2 (ribonucleoside-diphosphate reductase M2 subunit) and DHFR (dihydrofolate reductase), the new drug raltitrexed may be more specific to TYMS, but no published data are available for glioblastoma treatment." (PMID 21365010, 2011). "However, there are no publications to date linking TYMS to glioblastoma." (PMID 21365010, 2011).
head and neck cancer (9 papers, 1999 to 2025). A primary or metastatic malignant neoplasm affecting the head and neck. "We found that DHFR 19-pb ins/del (rs70991108) and TYMS 28-bp tandem repeat (rs34743033) polymorphisms have a protective effect against head and neck cancer." (PMID 33369477, 2020). "Here, we aimed to investigate the association of polymorphisms DNMT3B -149C/T (rs2424913), DNMT3B -283T/C (rs6087990), DNMT3B -579G/T (rs2424909), DHFR 19-pb ins/del (rs70991108), SHMT1 1420C/T (rs1979277), and TYMS 28-bp tandem repeat (rs34743033) with the risk of head and neck cancer." (PMID 33369477, 2020). "Thus, our findings reveal that DNMT3B -283T/C is associated with cancer risk, whereas DHFR 19-pb ins/del and TYMS 28-bp tandem repeat polymorphisms have a protective effect against head and neck cancer in relation to that in the control group." (PMID 33369477, 2020). "There has been previous evidence of differential expression of e.g. NEFH, ZRF2,TAF7L, ZNF541 and TYMS in head and neck cancer, related to HPV status." (PMID 38643268, 2024). "5-Fluorouracil (5-FU), an inhibitor of thymidylate synthetase, induces an intracellular increase in O2- levels in colon, rectum, and head and neck cancers." (PMID 32718084, 2020).
mesothelioma (9 papers, 2009 to 2025). A usually malignant and aggressive neoplasm of the mesothelium which is often associated with exposure to asbestos. "Several genes of the “salvage pathway” that recycle nucleobases were overexpressed, among them TYMS, encoding thymidylate synthase, the main target of the antifolate drug pemetrexed that is active in mesothelioma." (PMID 19662092, 2009). "TYMS was overexpressed, encoding thymidylate synthase, part of the “salvage pathway” in mammals and known as the target of the antifolate drug pemetrexed that is active in mesothelioma." (PMID 19662092, 2009). "We also found concomitant BMAL1 and TYMS overexpression indicating that this clock gene may also be an important driver of mesothelioma progression." (PMID 19662092, 2009). "For instance, a new generation of antifolates targeting TYMS such as Pemetrexed (PMX) or Raltitrexed (RTX) are used for the treatment of squamous cell carcinomas of the lung and mesotheliomas among many other tumors." (PMID 34454516, 2021). "Thymidylate synthase (TYMS) is elevated in numerous tumors and its overexpression corresponds to worsening clinical outcomes and has been correlated with drug resistance in malignant cells, including mesothelioma patients." (PMID 37894370, 2023). "Combination therapy of TYMS shRNA and pemetrexed also sensitized mesothelioma xenografts prolonging mouse survival, suggesting that the clinical benefit of pemetrexed as a first-line treatment for patients with malignant pleural mesothelioma and NSCLC could improve by downregulating TYMS." (PMID 37106126, 2023).
esophageal cancer (7 papers, 2014 to 2023). A primary or metastatic malignant neoplasm involving the esophagus. "An elevation of TYMS mRNA in esophageal cancer tissues was observed based on the analysis of GEPIA online database." (PMID 37682862, 2023). "GEPIA databases analysis showed that TYMS expression in esophageal cancer tissues was higher than that in normal tissues." (PMID 37682862, 2023). "In the present study, the analysis of GEPIA online database found that the expression of TYMS gene was generally up-regulated in human esophageal cancer, indicating that detection of TYMS expression could be used as an indicator for ESCC diagnosis." (PMID 37682862, 2023). "These mutation types largely recapitulate Signature 17 and for this reason nucleotide imbalance by TYMS inhibition is a plausible cause for the here observed 5-FU mutations as well, although the strong similarity with the process active in esophageal cancer is not easily explained." (PMID 31594944, 2019). "For instance, based on DepMap data we observed a significant cooperation between TYMS and CDKN2A in esophageal cancer cell lines." (PMID 34454516, 2021). "The expression levels of ERCC1, TYMS, TUBB3, RRM1 and TOP2A were determined using a microarray technique, while Spearman’s rank correlation analysis was used to determine the strength of the correlations between the expression levels of the biomarkers and the pathogenesis of esophageal cancer." (PMID 24926347, 2014).
acute lymphoblastic leukemia (6 papers, 2008 to 2021). Leukemia with an acute onset, characterized by the presence of lymphoblasts in the bone marrow and the peripheral blood. "Low expression of TYMS in lymphoblastic leukemia cells is associated with decreased antileukemic effects of MTX and increased risk of relapse." (PMID 34200242, 2021).
glioma (6 papers, 2011 to 2025). A benign or malignant brain and spinal cord tumor that arises from glial cells (astrocytes, oligodendrocytes, ependymal cells). "The Human Protein Atlas illustrated moderate or strong staining in 9 of 12 samples for TYMS and 5 out of 12 glioma samples for CDKN2A." (PMID 21365010, 2011). "This suggests that TYMS may be a therapeutic target for glioma cells, and further studies to test the efficacy of a folate-targeting drug in gliomas showing outlier expression for TYMS should be undertaken." (PMID 21365010, 2011).
leukemia (6 papers, 1997 to 2025). A malignant (clonal) hematologic disorder, involving hematopoietic stem cells and characterized by the presence of primitive or atypical myeloid or lymphoid cells in the bone marrow and the blood. "A previous study reported that a murine leukemia cell line acquired PEM resistance by decreasing the expression of SLC19A1 and FPGS without an increase in the TYMS expression." (PMID 29682186, 2018).
liver cancer (6 papers, 2020 to 2023). An epithelial or non-epithelial malignant neoplasm that arises from the liver. "Therefore, the expression levels of AURKA, BIRC5, CCNB1, CDK1, CDKN3 and TYMS served as diagnostic markers for liver cancer patients." (PMID 37393234, 2023). "Consistent with the results in cancer tissues, we observed that TYMS expression levels were higher in the liver cancer cell lines than in the normal liver cell line." (PMID 34858842, 2021). "Next, we found RRM2, TK1, and TYMS to be strongly and significantly induced by about ten-, six- and fourfold, respectively, in liver cancer patient datasets from TCGA." (PMID 32587247, 2020). "Knockdown of lincNMR, YBX1, TK1, and TYMS also significantly inhibited the colony-formation capacity of liver cancer cells." (PMID 32587247, 2020). "In summary, their regulation, their association with survival, and their correlation of expression links lincNMR, YBX1, RRM2, TK1, and TYMS to liver cancer and to each other, respectively." (PMID 32587247, 2020). "High TYMS expression predicts poor prognosis after liver cancer resection, suggesting that TYMS could be a reliable predictor of prognosis in patients with liver cancer resection." (PMID 34141464, 2021). "LincNMR and YBX1 mRNA expression significantly correlate in liver cancer patient samples as well as with RRM2, TK1, and TYMS mRNA expression." (PMID 32587247, 2020). "The lincNMR expression level significantly positively correlated with RRM2, TK1, and TYMS mRNA levels in HCC patient samples, further corroborating the strong link between lincNMR, these three regulators of nucleotide metabolism, and liver cancer." (PMID 32587247, 2020).
metastatic colorectal cancer (6 papers, 2008 to 2021). "Furthermore, we previously showed that elevated TYMS expression in CTCs was associated with poor prognosis among patients with metastatic colorectal cancer." (PMID 31247977, 2019). "TYMS has been reported as an important gene in diverse cancers, including red blood cell folate and homocysteine concentrations, and metastatic colorectal cancer." (PMID 32040444, 2020). "However, the only level IC clinical trial in our dataset showed contradictory evidence where metastatic colorectal cancer patients overexpressing TYMS had a trend towards better overall survival than the underexpressing cases." (PMID 27888622, 2017). "Among the gastrointestinal diseases targeted by both TYMS and BCL2L1, metastatic colorectal cancer ranked the first overall." (PMID 34141464, 2021).
osteosarcoma (6 papers, 2015 to 2024). A usually aggressive malignant bone-forming mesenchymal neoplasm, predominantly affecting adolescents and young adults. "Although the expression levels of TYMS in both osteosarcoma cell lines were identical, marked differences in the expression of this gene were detected between the medulloblastoma cell lines, with higher levels of TYMS found in Daoy cells with higher proliferation activity." (PMID 25739012, 2015).
triple-negative breast carcinoma (6 papers, 2019 to 2024). An invasive breast carcinoma which is negative for expression of estrogen receptor (ER), progesterone receptor (PR), and human epidermal growth factor receptor 2 (HER2). "It was reported that TYMP overexpression correlates with TYMS KO sensitivity in cell lines and antifolate treatment in triple negative breast cancer patients." (PMID 34454516, 2021).